PGM1 (phosphoglucomutase 1)
Description:
Catalyzes the reversible isomerization of alpha-D-glucose 1-phosphate to alpha-D-glucose 6-phosphate. The mechanism proceeds via the intermediate compound alpha-D-glucose 1,6-bisphosphate (Probable). This enzyme participates in both the breakdown and synthesis of glucose.
Synonyms: CDG1T; GSD14
Tractability: Small molecule: a structure with a bound ligand is known. Antibody: its Gene Ontology location is reachable by antibodies, with high confidence. PROTAC: ubiquitination databases record sites on it; its protein half-life has been measured.
Gene: Protein-coding gene on chromosome 1 (63,593,241 to 63,660,245, forward strand). Ensembl gene ENSG00000079739.
Subcellular location: Cytoplasm (Isoform 1)
Subcellular location (Human Protein Atlas): Cytosol
Pathways (Reactome):
Metabolism: Galactose catabolism; Glycogen breakdown (glycogenolysis); Glycogen synthesis
Disease: Defective PGM1 causes PGM1-CDG
Immune System: Neutrophil degranulation
Gene Ontology:
Molecular function: magnesium ion binding; phosphoglucomutase activity; protein binding; intramolecular phosphotransferase activity
Biological process: galactose catabolic process via UDP-galactose, Leloir pathway; glucose metabolic process; glycogen catabolic process; gluconeogenesis; glycolytic process; carbohydrate metabolic process
Cellular component: cytosol; extracellular exosome; cytoplasm; extracellular region; ficolin-1-rich granule lumen; tertiary granule lumen
Genetic constraint (gnomAD): Loss-of-function variants: 51 observed, 54.17 expected, observed/expected ratio (o/e) 0.94, 90% interval 0.75 to 1.19. The upper end of that interval is the gene's LOEUF score, 1.19, which puts it in group 5 of 6, group 1 being the genes least tolerant of losing a copy. Missense variants: 720 observed, 756.6 expected, observed/expected ratio (o/e) 0.95, 90% interval 0.89 to 1.01. Synonymous variants: 287 observed, 283.89 expected, observed/expected ratio (o/e) 1.01, 90% interval 0.92 to 1.12.
Gene-disease validity (ClinGen):
ClinGen rates the evidence that PGM1 causes each of these diseases.
PGM1-congenital disorder of glycosylation (autosomal recessive): Definitive.
Homologues: Orthologues: mouse Pgm1 (97% identical), rat Pgm1 (97% identical), chimpanzee PGM1 (92% identical), rabbit PGM1 (91% identical), dog PGM1 (90% identical), guinea pig PGM1 (89% identical), macaque PGM1 (88% identical), Caenorhabditis elegans pgm-1 (59% identical), Drosophila melanogaster Pgm1 (58% identical). Paralogues in human: PGM5 (65% identical), PGM2 (21% identical), PGM2L1 (21% identical), PGM3 (15% identical), HPRT1 (8% identical), PRTFDC1 (7% identical).
Diseases named in the same sentence as PGM1 in open-access papers:
PGM1 is named in the same sentence as 86 diseases in open-access papers, as found by Europe PMC text mining. Sharing a sentence is not in itself a finding about the gene and the disease. The quoted sentences say what the papers report.
Hypoglycemia (11 papers, 2015 to 2023). A decreased concentration of glucose in the blood. "PGM1 deficiency is an autosomal recessive disorder characterized by a highly heterogenous clinical spectrum, including hypoglycemia, cleft palate, liver dysfunction, growth delay, exercise intolerance, and dilated cardiomyopathy." (PMID 37175952, 2023). "PGM1 gene encodes the enzyme PGM1 and recessive loss-of-function mutations in PGM1 cause hypoglycemia." (PMID 32185602, 2020). "These patients were found to have recessive inactivating PGM1 mutations, which has previously demonstrated to be related to the development of hypoglycaemia, similar to glycogenoses." (PMID 30873120, 2019). "Phosphoglucomutase 1 (PGM1) is involved in glycogen metabolism and a loss-of-function mutation in the PGM1 gene has been shown to be associated with hypoglycaemia." (PMID 28855921, 2017). "Recently, a recessive loss-of-function mutation in the PGM1 gene that encodes the enzyme PGM1 has been shown to be associated with hypoglycaemia, similar to glycogenosis." (PMID 29280746, 2017). "However, due to abnormal glycogenolysis in PGM1 deficiency, frequent feedings are needed to prevent hypoglycemia." (PMID 32071842, 2020). "Most patients with phosphoglucomutase 1 deficiency (PGM1-CDG) develop hypoglycaemia, which seems to be because of multifactorial: hyperinsulinism, inappropriate counter-regulatory hormonal response (low cortisol), impaired glucose release from glycogen during fasting and malnutrition." (PMID 33179602, 2020). "Children with PGM1 mutation presented with postprandial HH and fasting hyperketotic hypoglycemia." (PMID 32185602, 2020). "The study has also reported that hypoglycaemia might occur in PGM1 deficient patients by starving and would be exaggerated by strong exercise." (PMID 30873120, 2019). "PGM1 deficiency has been described in a patient with myopathy and exercise induced hypoglycemia." (PMID 31805863, 2019).
congenital disorder of glycosylation (8 papers, 2016 to 2026). Congenital disorder of glycosylation (CDG) is a fast growing group of inborn errors of metabolism characterized by defective activity of enzymes that participate in glycosylation (modification of proteins and other macromolecules by adding and processing of oligosaccharide side chains). "Pathogenic variants in the PGM1 gene are associated with phosphoglucomutase-1 (PGM1)-congenital disorders of glycosylation (CDG)." (PMID 40358162, 2025). "PGM1 deficiency resulted in a mixed phenotype of a Glycogen Storage Disorder and a Congenital Disorder of Glycosylation (CDG)." (PMID 36514049, 2022). "Congenital deficiency of PGM-1 is associated with a mixed disorder of N-glycosylation and patients affected with this disease show features of both type 1 and type 2 congenital glycosylation disorders." (PMID 27707936, 2016). "Phosphoglucomutase-1-congenital disorder of glycosylation (PGM1-CDG) is a rare genetic disorder caused by biallelic variants in the PGM1 gene, leading to the deficiency of the PGM1 enzyme." (PMID 38968673, 2024). "Some congenital disorders of glycosylation (CDGs) are caused by abnormal sugar nucleotide metabolism, such as defects in GDP-Man (PMM2-CDG) biosynthesis or an unbalanced UDP-Gal/UDP-GlcNAc ratio (PGM1-CDG)." (PMID 35422047, 2022). "PGM1 deficiency was known to be a congenital disorder of glycosylation (CDG) due to several SNVs in PGM1." (PMID 41008716, 2025). "Next, we used the developed technology to study perturbances in nucleotide sugar biosynthesis in phosphoglucomutase 1 (PGM1) deficiency (MIM#614921), a congenital disorder of glycosylation (CDG) affecting the synthesis of the nucleotide sugars UDP-Glc and UDP-Gal." (PMID 37443799, 2023). "In addition, we analyzed data collected in PGM1-CDG individuals currently participating in Frontiers in Congenital Disorders of Glycosylation (FCDGC) Natural History study (Clinical and Basic Investigations into Congenital Disorders of Glycosylation ClinicalTrials.gov ID: NCT04199000)." (PMID 38968673, 2024).
glycogen storage disease (7 papers, 2017 to 2023). "PGM1 deficiency in humans is associated with glycogen storage disease and a congenital disorder of glycosylation." (PMID 33755012, 2021). "Mutations in PGM1 typically show a broad range of clinical manifestations resembling glycogenosis (Type XIV) as well as mixed-type congenital disorders of glycosylation (CDG type1t)." (PMID 30873120, 2019). "Clinical studies have shown that mutations in the PGM1 gene may cause PGM1 deficiency, an inborn error of metabolism previously classified as a glycogen storage disease, and PGM1 deficiency was recently also shown to be a congenital disorder of glycosylation." (PMID 32221390, 2020). "Clinical studies have shown that mutations within the PGM1 are associated with an inborn error in metabolism previously classified as a glycogen storage disease, and a defect in PGM1 has recently been shown to be a congenital glycation disease." (PMID 35251177, 2022). "Glucose 6-phosphate flows mostly into glycolysis for energy production, while glucose 1-phosphate is the substrate for UDP-glucose synthesis, which is the building block of glycogen (PGM1-CDG is also considered a glycogen storage disorder) and of glycosylation." (PMID 37239976, 2023).
hepatocellular carcinoma (7 papers, 2018 to 2025). A malignant tumor that arises from hepatocytes. "Here, we show that PGM1 is down-regulated in hepatocellular carcinoma (HCC), which is associated with the malignancy and poor prognosis of HCC." (PMID 30335765, 2018). "We notice that PGM1 inhibited malignant progression of hepatocellular carcinoma, which seems to contradict conclusions of other studies." (PMID 34507580, 2021). "The effect of the expression level of PGM1 on cancer cells varies depending on the cell type and knockdown or deletion of the PGM1 gene inhibits glycogen synthesis and disruption of glycolysis, which promotes the proliferation and growth of hepatocellular carcinoma cells." (PMID 38164393, 2023). "PGM1 inhibits hepatocellular carcinoma cell (HCC) proliferation and growth by utilizing sufficient extracellular glucose to convert glycogen, while deletion of the PGM1 gene inhibits glycogen synthesis and leads to glycolysis of additional glucose, thus promoting tumor cell proliferation and growth." (PMID 35614441, 2022).
cardiomyopathy (5 papers, 2020 to 2026). A disease of the heart muscle or myocardium proper. "Missense variants in PGM1 are known to cause an inborn error of metabolism, called PGM1 deficiency, that manifests with a wide range of symptoms, including bifid uvula, cleft palate, and cardiomyopathy." (PMID 32847609, 2020). "These mechanistic insights offer a foundation for developing targeted therapies for PGM1-CDG and potentially other cardiomyopathies involving Z-disk dysfunction." (PMID 41723528, 2026). "Phosphoglucomutase 1 (PGM1)-CDG has a complex phenotype characterized by hepatopathy, myopathy, exercise-induced rhabdomyolysis, cardiomyopathy, bifid uvula, growth retardation, coagulation and endocrine alterations." (PMID 35422763, 2022). "As far as PGM1-CDG is concerned, liver involvement is observed in the multisystem phenotype (including congenital malformations, cardiomyopathy, variable endocrine and hematological abnormalities and no neurological disease); it has not been described in the muscular form of PGM1-CDG." (PMID 34291020, 2021).
dilated cardiomyopathy (5 papers, 2021 to 2025). Cardiomyopathy which is characterized by dilation and contractile dysfunction of the left and right ventricles. "Phosphoglucomutase-1 deficiency (CDG-PGM1) is a rare subtype often presenting with early cardiac involvement, including congenital heart disease and dilated cardiomyopathy." (PMID 41306474, 2025). "PGM1 deficiency is recognized as an inherited metabolic disorder (CDG1T) that is associated with a variety of phenotypes, including exercise intolerance, dilated cardiomyopathy, and liver disease, indicating that PGM1 plays a role in glucose metabolism." (PMID 35614441, 2022).
lung carcinoma (5 papers, 2021 to 2025). "In another study, it was shown that elevated levels of PGM1 in lung cancer tissues through AMPK activation under glucose-deprived conditions correlated with poor survival in those patients." (PMID 40796729, 2025). "For example, AMPK‐dependent phosphorylation of HDAC8 promotes lung cancer cell survival under glucose starvation via regulating PGM1 expression." (PMID 34351079, 2021). "Notably, it has been noted that high expression of PGM1 induces the survival and proliferation of lung cancer cells, whereas reduced expression of PGM1 decreases the proliferation of lung cancer cells." (PMID 38164393, 2023). "In another study, glucose deprivation activated AMP-activated protein kinase-dependent HDAC8 phosphorylation in lung cancer, triggering the elevated expression of PGM1 and promoting the malignant progression of lung cancer, suggesting that PGM1 is a promising anticancer therapeutic target." (PMID 35251177, 2022).
breast carcinoma (4 papers, 2012 to 2023). "For example, the PGM1 of key genes under the MCF7 cell line, is proven to be associated with breast cancer." (PMID 36677903, 2023). "It was recently found that the roles played by PGM1 in glycogen and glucose metabolism are responsible for suppressing the proliferation of cervical and breast cancer cells, and our current results support those findings." (PMID 35614441, 2022).
liver cancer (4 papers, 2019 to 2025). An epithelial or non-epithelial malignant neoplasm that arises from the liver. "Recent investigations have shown that PGM1 blocks liver cancer progression by regulating glucose trafficking." (PMID 35614441, 2022). "For example, PGM1 gene defects damage hepatocyte homeostasis via the central metabolic pathway and then affect the growth of liver cancer cells." (PMID 31582909, 2019). "However, PGM1 is involved in tumor suppression in liver cancer." (PMID 35252177, 2022).
cervical cancer (3 papers, 2018 to 2022). A primary or metastatic malignant neoplasm involving the cervix. "Under repetitive glucose depletion, depletion of PGM1 decreases glycogen content and the rates of glycogenolysis and glycogenesis, subsequently suppressing the proliferation of breast and cervical cancer cells." (PMID 30335765, 2018). "A recent study shows that depletion of PGM1 decreases glycogen content and the rates of glycogenolysis and glycogenesis, which subsequently suppresses the proliferation of breast and cervical cancer cells under long-term repetitive glucose depletion." (PMID 30335765, 2018). "A publicly available DNA microarray dataset revealed that three of the candidates (PGM1, FNDC3B, and IGF2R) were aberrantly expressed in cervical cancer tissues relative to normal cervix tissues." (PMID 31748500, 2019). "After multivariate Cox regression analysis, eight genes were identified as key predictors of HLA-G-driven DEGs in the prognostic risk model for predicting the overall survival of patients with cervical cancer, including CD46, LGALS9, PGM1, SPRY4, CACNB3, PLIN2, MSMO1, and DAGLB." (PMID 35924232, 2022).
heart failure (3 papers, 2021 to 2025). Inability of the heart to pump blood at an adequate rate to meet tissue metabolic requirements. "Patient with PGM1-CDG manifested progressive cardiac insufficiency and liver impairment (hepatomegaly, elevated serum transaminases) since 4 years of age." (PMID 33407696, 2021).
hyperinsulinism (3 papers, 2020 to 2023). Abnormally high levels of insulin in the blood. "The entities reported to be associated with hyperinsulinism are PMM2-CDG (CDG1a), MPI-CDG (CDG1b), ALG3-CDG (CDG1d), and PGM1-CDG (CDG1t) (reviewed by 97, 98)." (PMID 37065762, 2023).
type 2 diabetes mellitus (3 papers, 2013 to 2025). A type of diabetes mellitus that is characterized by insulin resistance or desensitization and increased blood glucose levels. "As indicated in earlier research, there is a demonstrable association between the PGM1 phenotypes, rs1126728 or rs11208257, and various pathological conditions, including type 2 diabetes mellitus, low birthweight, and repeated spontaneous abortion." (PMID 41008716, 2025). "The PGM1 polymorphism has been associated with various pathological conditions, including type 2 diabetes mellitus, low birthweight, and repeated spontaneous abortion, likely due to slight differences in enzyme activity between polymorphisms." (PMID 41008716, 2025). "Finally, a region on chromosome 1p31.3, near PGM1, co-localised (H4PP=0.91), with the minor T allele at the type 2 diabetes index variant rs2269247 (C>T) decreasing risk of type 2 diabetes (OR 0.96, p=4.6×10-7) and increasing risk of type 1 diabetes (OR 1.15, p=1.9×10-6)." (PMID 33830302, 2021).
galactosemia (2 papers, 2022 to 2023). "Although galactonate is mostly detected in pathological conditions, such as in patients affected by galactosemia [OMIM#230400], further investigations should be planned in this direction to evaluate its presence and contribution in PGM1 deficiency." (PMID 37175952, 2023). "Eventually, whole exome sequencing excluded the galactosemia and revealed PGM1-CDG." (PMID 36873091, 2022).
gastric cancer (2 papers, 2021 to 2022). A primary or metastatic malignant neoplasm involving the stomach. "Phosphoglucomutase 1 (PGM1) is mainly involved in glucose catabolism and synthesis and enhances the proliferation and metastasis of gastric cancer cells." (PMID 35252177, 2022). "However, the role of PGM1 in gastric cancer (GC) remains unclear." (PMID 34507580, 2021).
glioblastoma (2 papers, 2023 to 2024). The most malignant astrocytic tumor (WHO grade IV). "Interestingly, PGM1, a brain isoform, is highly expressed in C6 cells from rat glioma cells, high-grade human astrocytoma, and human glioblastoma samples." (PMID 38139462, 2023). "Similarly, the knockdown of PGM1 resulted in a decrease in the cell viability of glioma cells; furthermore, in glioblastoma xenografts the knockdown of PGM1 led to an increment of 14.5% in the survival rate of the mice." (PMID 38139462, 2023).
liver disease (2 papers, 2021 to 2022). "The authors classified CDG based on liver involvement into two main groups: one with predominant/isolated liver involvement (MPI-CDG, CCDC115-CDG, TMEM199-CDG, ATP6AP1-CDG) and the other associated with liver disease (PMM2-CDG, ALG1-CDG, ALG3-CDG, ALG8-CDG, ALG9-CDG, PGM1-CDG)." (PMID 34291020, 2021).
metabolic myopathy (2 papers, 2020 to 2023). A group of rare inherited disorders characterized by a deficiency of enzymes that are involved in metabolic pathways that affect muscles. "Thus far, it has been estimated that over 50% of PGM1-deficient patients present with metabolic myopathy ranging from mild to severe exercise intolerance, muscle weakness, and fatigability, hypotonia, and rhabdomyolysis." (PMID 37175952, 2023). "If our findings will be corroborated by future studies in human muscle models, in the future other metabolites beyond galactose should be investigated as potential targets for treatment design to address metabolic myopathy in PGM1-CDG patients." (PMID 37175952, 2023).
metastatic tumors (2 papers, 2025). "In metastatic tumors, pathway and TF analyses revealed strong hypoxia-inducible factor-1α–driven hypoxia activation, influencing glycolysis (SLC2A1, SLC2A3, PGK1, PDK1, PGM1, and ALDOA), angiogenesis (ANGPTL4 and ADM), and survival in low oxygen (BNIP3, BNIP3L, and NDRG1)." (PMID 40736012, 2025). "Four other glycolytic genes, ENO1, PGM1, LDHB, and PGK19, were upregulated in metastatic tumors compared to non-metastatic tumors." (PMID 40821334, 2025).
Obesity (2 papers, 2015 to 2019). Accumulation of substantial excess body fat. "PGM1 is associated with diseases such as hypertension, obesity and cardiovascular disease." (PMID 26042666, 2015). "Some researches verified that PGM1 (Phosphoglucomutase-1) and FTO (Fat mass and obesity-associated protein) that located on chromosome 6 significantly affected muscle development and obesity, respectively." (PMID 31024621, 2019).
osteosarcoma (2 papers, 2022). A usually aggressive malignant bone-forming mesenchymal neoplasm, predominantly affecting adolescents and young adults. "The expression of BNIP3, SLC38A5, CKMT2, CXCL11, SLC5A3, S100A3, and PGM1 genes was verified in osteosarcoma cells (Saos-2 and 143B) and normal osteoblasts (hFOB1.19)." (PMID 36578780, 2022). "The results of univariate Cox regression analysis showed SLC2A1, ENO1, FBP1 and PGM1, while multivariate COX regression analysis showed that SLC2A1 and FBP1 could indicate the prognostic risk of patients in osteosarcoma." (PMID 36316355, 2022).
ovarian carcinoma (2 papers, 2021). A malignant neoplasm originating from the surface ovarian epithelium. "PGM1 was also reported to promote progression in lung and ovarian cancer." (PMID 34507580, 2021). "These cytokines then induced the phosphorylation of phosphoglucomutase 1 (PGM1), which promoted glycogen catabolism and activated glycolysis and the pentose phosphate pathway (PPP) in ovarian cancer cells, leading to the proliferation, invasion, and early metastasis of cancer cells." (PMID 34373744, 2021).